CEL (carboxyl ester lipase)
Description:
Catalyzes the hydrolysis of a wide range of substrates including cholesteryl esters, phospholipids, lysophospholipids, di- and tri-acylglycerols, and fatty acid esters of hydroxy fatty acids (FAHFAs). Preferentially hydrolyzes FAHFAs with the ester bond further away from the carboxylate. Unsaturated FAHFAs are hydrolyzed more quickly than saturated FAHFAs (By similarity). Has an essential role in the complete digestion of dietary lipids and their intestinal absorption, along with the absorption of fat-soluble vitamins.
Synonyms: BAL; BSSL; MODY8; BSDL; CELL; CEase; FAP; FAPP
Tractability: Small molecule: it has a high-quality binding pocket; it belongs to a druggable protein family. Antibody: UniProt places it where antibodies can reach, with high confidence; its Gene Ontology location is reachable by antibodies, with high confidence; UniProt predicts a signal peptide or a membrane-spanning region. PROTAC: a small molecule that binds it is known.
Target class: Enzyme; Hydrolase
Gene: Protein-coding gene on chromosome 9 (133,061,981 to 133,071,861, forward strand). Ensembl gene ENSG00000170835.
Subcellular location: Secreted
Pathways (Reactome):
Developmental Biology: Developmental Lineage of Pancreatic Acinar Cells
Digestion and absorption: Digestion of dietary lipid
Gene Ontology:
Molecular function: acetylesterase activity; protein binding; sterol ester esterase activity; triacylglycerol lipase activity; catalytic activity; heparin binding; hydrolase activity; retinyl-palmitate esterase activity; carboxylesterase activity
Biological process: intestinal cholesterol absorption; pancreatic juice secretion; ceramide catabolic process; lipid metabolic process; retinol metabolic process
Cellular component: extracellular exosome; extracellular region; cytoplasm
Genetic constraint (gnomAD): Loss-of-function variants: 38 observed, 51.23 expected, observed/expected ratio (o/e) 0.74, 90% interval 0.57 to 0.97. The upper end of that interval is the gene's LOEUF score, 0.97, which puts it in group 4 of 6, group 1 being the genes least tolerant of losing a copy. Missense variants: 615 observed, 719.34 expected, observed/expected ratio (o/e) 0.85, 90% interval 0.8 to 0.91. Synonymous variants: 293 observed, 298.17 expected, observed/expected ratio (o/e) 0.98, 90% interval 0.89 to 1.08.
Gene-disease validity (ClinGen):
ClinGen rates the evidence that CEL causes each of these diseases.
maturity-onset diabetes of the young type 8 (autosomal dominant): Moderate.
Homologues: Orthologues: macaque CEL (83% identical), pig CEL (66% identical), mouse Cel (63% identical), rat Cel (63% identical), rabbit CEL (61% identical), guinea pig CEL (59% identical), tropical clawed frog cel.2 (47% identical), zebrafish cel.2 (42% identical), zebrafish cel.1 (42% identical), Caenorhabditis elegans ace-3 (21% identical), Drosophila melanogaster Jhe (20% identical), Drosophila melanogaster CG4382 (20% identical), and 39 more. Paralogues in human: BCHE (24% identical), CES1 (24% identical), ACHE (24% identical), NLGN1 (23% identical), NLGN3 (23% identical), NLGN4X (23% identical), NLGN4Y (23% identical), NLGN2 (23% identical), CES5A (22% identical), CES3 (22% identical), CES2 (22% identical), CES4A (21% identical), and 1 more.